PALB2 (partner and localizer of BRCA2)
Diseases named in the same sentence as PALB2 in open-access papers (continued):
Sharing a sentence is not in itself a finding about the gene and the disease.
Lymphoid Tumours (1 paper, 2016). "The clinical features of the two siblings (II-4 and II-5) shown to have the biallelic PALB2 mutations included abnormally small size, dysmorphic facies and lymphoid tumour development." (PMID 26990772, 2016). "Nevertheless, the presence of a lymphoid tumour in both affected individuals does raise the interesting possibility that PALB2 may represent a novel tumour suppressor of lymphoid malignancies in a manner similar to ATM and NBN." (PMID 26990772, 2016).
lymphoma (1 paper, 2025). A malignant (clonal) proliferation of B- lymphocytes or T- lymphocytes which involves the lymph nodes, bone marrow and/or extranodal sites. "Since the patient was exposed to chemotherapy due to lymphoma prior to the development of secondary malignancy and the variant is classified as an aberration of unknown significance, the causative role of the PALB2 variant remains uncertain." (PMID 40040726, 2025).
medullary breast carcinoma (1 paper, 2010). An infiltrating breast carcinoma with a relatively favorable prognosis. "We are the first to present a PALB2 truncating mutation in a patient with medullary breast carcinoma." (PMID 20122277, 2010).
metastatic melanoma (1 paper, 2022). A melanoma that has spread from its primary site to another anatomic site. "Indeed, a recent case report showed the partial response of olaparib as monotherapy in a metastatic melanoma patient carrying a PALB2 mutation, who has progressed in immunotherapy." (PMID 35563772, 2022).
Multiple Endocrine Neoplasia syndromes (1 paper, 2019). "Beyond Multiple Endocrine Neoplasia syndromes, however, we report the first cases of patients with a PALB2, an APC and a NTHL1 pathogenic variants and both malignancies." (PMID 31592449, 2019).
myeloid sarcoma (1 paper, 2021). A tumor mass composed of myeloblasts or immature myeloid cells. "We present the finding of an infant with thoracic and intraspinal aleukemic myeloid sarcoma with a rare germline PALB2 variant (p.A1079S)." (PMID 34382369, 2021). "Here, we report an infant with an extended atypic localization of myeloid sarcoma as isolated manifestation of an AML with a paternally inherited rare PALB2 germline variation." (PMID 34382369, 2021).
myxofibrosarcoma (1 paper, 2025). A malignant fibroblastic neoplasm arising from the soft tissue. "Of note, a patient with myxofibrosarcoma who had an ongoing deep and sustained response harbored a mutation in PALB2, which is involved in the recruitment of BRCA2 and RAD51 to DNA breaks in the homologous recombination pathway." (PMID 41145467, 2025).
NBS-like disorder (1 paper, 2015). "It is unlikely transformed cells can survive without MRE11A, RAD50, ATRIP or PALB2 although significantly reduced levels may be tolerated, as evidenced by the ATR expression in Seckel syndrome and hypomorphic MRE11A and RAD50 mutations in ATLD and NBS-like disorder patients, respectively." (PMID 26438152, 2015).
neuroendocrine carcinoma (1 paper, 2026). A malignant neuroendocrine neoplasm composed of cells containing secretory granules that stain positive for NSE and chromogranin.
non-melanoma skin carcinoma (1 paper, 2021). "Moreover, we identify the PALB2 c.1592delT mutation as a potential susceptibility factor for non-melanoma skin cancer in the high cancer risk families carrying this founder mutation." (PMID 34084283, 2021).
orbital tumor (1 paper, 2023). "An NGS assay performed on the orbital tumor showed a PALB2 mutation, and she also had a known germline PALB2 mutation." (PMID 37173992, 2023).
osteosarcoma (1 paper, 2021). A usually aggressive malignant bone-forming mesenchymal neoplasm, predominantly affecting adolescents and young adults. "To illustrate this case, we outline the clinical course of an 8‐year‐old patient in whom genetically simple primary osteosarcoma recurred as highly rearranged HRRD‐positive metastases after acquiring PALB2 deletions." (PMID 33963544, 2021).
pineocytoma (1 paper, 2025). "In the analyzed pineocytoma and PAT samples no mutations were found except for a PALB2 mutation in one pineocytoma." (PMID 41291966, 2025). "Whereas the pineocytomas showed no pathogenic variants in NGS panel sequencing except for a heterozygous PALB2 variant in a single case, hotspot KBTBD4 inframe insertions were found in all 4 PPTID-B samples and 9 of 11 PPTID-A cases." (PMID 41291966, 2025).
squamous cell carcinoma (1 paper, 2021). A carcinoma arising from squamous epithelial cells. "Mutations of all; PALB2, BRCA1, BRCA2 and CHEK2 were most frequent in cutaneous squamous cell carcinomas covering ~60% of mutations in each of the genes." (PMID 34084283, 2021).
sweat gland tumors (1 paper, 2025). "We have described sweat gland tumors with HRD-associated germline PALB2, BRCA1, and PMS2 mutations." (PMID 40948682, 2025).
synovial sarcoma (1 paper, 2026). "The most common molecular alterations (excluding canonical SS18::SSX fusions in synovial sarcoma) involved ATM (18%), ARID1A (9%), CTNNB1 (9%), PALB2 (9%), and NF1 (9%), while 46% of profiled cases showed no detectable alterations." (PMID 41504936, 2026).
vulvar cancer (1 paper, 2023). "The c.79G>T variant creates a premature translational stop signal in the PALB2 gene, causing an absent or disrupted protein product which was associated with breast and vulvar cancer." (PMID 36980780, 2023).
cancer (401 papers, 2008 to 2026). A tumor composed of atypical neoplastic, often pleomorphic cells that invade other tissues. "All-cause mortality was increased among PALB2-heterozygotes (HR 1.61-1.67), and survival after cancer diagnosis was reduced." (PMID 41959818, 2026). "The cancer risk associated with PALB2 mutations within a gene and the type and location of the mutation strongly influence the associated risk." (PMID 41049353, 2025). "Germline testing (Tempus xG+) confirmed a pathogenic heterozygous PALB2 (p.Met723Valfs) mutation, consistent with PALB2-related cancer susceptibility." (PMID 40948682, 2025). "This study reported the p.Gln559Ter variant in PALB2 for the first time in a young patient with an age of onset between 31 and 35 years and with a family history of cancer in first- and second-degree relatives." (PMID 40869938, 2025). "Heterozygous carriers of pathogenic variants in FA pathway genes—most notably FANCD1/BRCA2 and FANCN/PALB2—are at increased risk for various cancers, particularly breast, ovarian, and pancreatic malignancies." (PMID 41155398, 2025). "Pedigrees of BRCA1/2 and PALB2 variant carrier cases indicated that breast and other cancer types are often accumulated in these families, providing further evidence for the presence of inherited risk factors." (PMID 40009290, 2025). "Individuals with biallelic pathogenic variants in FANCD1/BRCA2 and FANCN/PALB2 exhibit a unique cancer predisposition." (PMID 40970532, 2025). "Given the recent advancements in surveillance and treatment options for PALB2-associated cancers, identifying carriers of PALB2 variants is essential for effective management and intervention." (PMID 39409938, 2024). "In the overall MaBC and FBC cohorts, we compared mutational prevalence in cancer susceptibility genes (CSG) (ATM/BRCA1/BRCA2/CHEK2/PALB2)." (PMID 39049124, 2024). "The chemotherapeutic agent CX-5461, or pidnarulex, has been fast-tracked by the United States Food and Drug Administration for early-stage clinical studies of BRCA1-, BRCA2- and PALB2-mutated cancers." (PMID 38036782, 2024). "Among patients with FA, the highest cancer risks are observed in patients with biallelic pathogenic variants in BRCA2 or PALB2." (PMID 38685107, 2024). "Recommended guidelines for early detection and cancer risk reduction in women with PVs in moderate-penetrance risk genes increasing lifetime cumulative risk over 20%, including PALB2, ATM, and CHEK2, are starting to become available." (PMID 38339330, 2024). "As testing for PALB2 variants can be important for cancer risk assessment and screening as well as pregnancy planning, our patient’s maternal relatives were offered genetic counselling, but they have not responded to the invitation so far." (PMID 38817905, 2024). "Our analysis suggests that undergoing both RRSO and RRM is the most effective and cost-effective option for BRCA1, BRCA2, and PALB2 PV carriers, with younger surgery ages for those with higher cancer risk preventing more cancers." (PMID 38334999, 2024). "Understanding the frequency of PALB2 variants can help in identifying individuals at higher risk for these cancers and guide the development of targeted screening and prevention strategies." (PMID 39409938, 2024). "The mutation in the structure of PALB2 protein increases the riskof cancer by 14% and 35% among 50- and 70- year old individuals, respectively." (PMID 39430039, 2023). "PALB2 testing is important because of the associated high cancer risk, and including patients carrying P/LP variants in preventive and screening programs can improve their life expectancy similarly to BRCA1/2 carriers." (PMID 37686625, 2023). "Overall, 15 patients out of 521 (2.9%) showed PVs and LPVs in five cancer-predisposing genes other than BRCA1/2 (PALB2, CHEK2, ATM, RAD51C, and RAD51D)." (PMID 37628581, 2023). "On the other hand, the cancer risks associated with PVs in PALB2 are becoming more and more similar to those for BRCA1 and BRCA21,31." (PMID 37237042, 2023).
cancer (continued). "In a cohort of Italian MBC (523 patients) analysed with a panel of 50 cancer-associated genes, PALB2 and RAD51D gene variants were significantly associated with MBC risk." (PMID 37762649, 2023). "Variants in three genes (RPN1, HRAS and PALB2) were carried by several individuals with cancer in extended cohort." (PMID 36845707, 2023). "The PARP inhibitors (PARPi) successfully used in the treatment of BRCA-deficient cancers through synthetic lethality can also be applied to treat the cancer types with PALB2 pathogenic variation." (PMID 37511102, 2023). "Based on the genetic testing of cancer patients and their relatives in recent years, a large number of PALB2 variants have been discovered." (PMID 35853885, 2022). "The KEGG results showed PALB2 was associated with several cancer-associated pathways, including ubiquitin-mediated proteolysis, protein processing in the endoplasmic reticulum, autophagy, DNA replication, RNA transport, and cell cycle." (PMID 36158641, 2022). "Other genes with germline mutations had been reported to confer moderate cancer risk, such as ATM, CHECK2, and PALB2, which are also associated with other cancers." (PMID 35406420, 2022). "As such, caution is required when assessing the cancer risk of individuals with these PALB2 variants." (PMID 35853885, 2022). "Increased expression of homologous recombination (HR) genes such as PALB2 is associated with poor prognosis, high grade cancers, probably because HR genes are expressed predominantly in the S and G2/M parts of the cell cycle when HR occurs." (PMID 35779338, 2022). "Recent studies reveal that the pathogenic variants of PALB2 are associated with some cancers, such as breast, pancreatic, and ovarian cancers." (PMID 36158641, 2022). "The physiological importance of PALB2 is further highlighted by the recent large-scale functional analysis of PALB2 mutations in cancer patients." (PMID 36269050, 2022). "PALB2 has an important role in cancer development and progression as even heterozygous mutations appear to contribute to early events of oncogenesis." (PMID 35875117, 2022). "Together these results describe the first ever CAC case with a BRCAness genetic background, evaluate combinatorial DNA repair targeting, and provide a data resource for further analyses of DNA repair targeting in PALB2 deficient cancers." (PMID 34084283, 2021). "The role of key interaction amino acids and known cancer-associated PALB2 mutations was assayed through solution binding studies." (PMID 34946951, 2021). "Compared to the frequency of mutations in cancer-free controls from our previous studies, we observed statistically significant associations for PALB2 (OR = 11.66 p < 0.001) and for CHEK2 truncating mutations (OR = 2.93; p = 0.02)." (PMID 34461861, 2021). "One signature is associated with biallelic inactivation of BRCA1 and BRCA2 (due to HR deficiency) but has also been demonstrated in breast and pancreatic cancers from individuals with constitutional PALB2 truncating variants." (PMID 33854214, 2021). "Patient #18 with germline PALB2 mutation presented with ~ 10 cm cancer, had large 3.5 cm residual cancer following neoadjuvant anthracyclines and taxanes." (PMID 33420229, 2021). "Genes that are essential in eHAP cells include cancer risk genes such as PALB2, BARD1, RAD51C, and RAD51D, which have thousands of variants recorded in ClinVar." (PMID 33691754, 2021). "As expected, PALB2 c.3235G>T and its surrounding nucleotides are rarely mutated in the germline of healthy individuals, while they show a high frequency within cancer." (PMID 34382369, 2021). "Otherwise, when PALB2 mutations occur as monoallelic, they are associated with predisposition to breast and other cancers." (PMID 33718150, 2021). "In our study, the EC patient carrying the PALB2 variant had a strong family history of various cancers, with carrier or obligate carrier status confirmed for relatives with breast, colon and EC." (PMID 33917078, 2021).
cancer (continued). "SLC25A13 c.852_855delCATA (n = 7), GJB2 c.235delC (n = 7), and PALB2 c.C2257T (n = 2) were the variants observed more than once across cancers." (PMID 33889545, 2021). "PALB2 is another gene of which bi-allelic germ line PGVs can cause FA, also termed FANCN, with a similar clinical presentation and cancer spectrum as FA caused by BRCA2 PGVs including childhood solid tumours." (PMID 34680915, 2021). "The tumor suppressor protein partner and localizer of BRCA2 (PALB2) orchestrates the interactions between breast cancer susceptibility proteins 1 and 2 (BRCA1, -2) that are critical for genome stability, homologous recombination (HR) and DNA repair." (PMID 34946951, 2021). "Seven kinds of RAD52i have been proposed, and some of these compounds are approved by the FDA, indicating that RAD52i is an attractive approach for BRCA1-, BRCA2-, RAD51 paralog-, and PALB2-deficient cancer." (PMID 33922657, 2021). "Some authors have tried to set up different methods for VUS classification for the BRCA1, BRCA2, and the PALB2 genes in order to predict variant pathogenicity and the resulting susceptibility to cancer." (PMID 34206535, 2021). "In this network, four FA-gene products (FANCD1/J/N/S) are previously well-known DNA damage repair proteins (respectively for BRCA1/2, BRIP1 and PALB2), conferring human cancer susceptibility in breast, ovary, prostate, and/or others." (PMID 33099537, 2020). "The ClinGen Gene module does not appear to be of clinical utility for this patient, with the potential exception of the frameshift deletion affecting PALB2, which has been associated with susceptibility to several cancer types." (PMID 32228266, 2020). "Such PALB2-null cancers all exhibited HR deficiency, with some tumors even showing HR deficiency while the wild type allele was retained, suggesting that also alternative mechanisms for PALB2 LOF can be in play." (PMID 33195396, 2020). "Generally, assessment of pathogenicity of such variants of uncertain significance (VUS) would rely mostly on in silico analysis, co-segregation of the variant with cancer, co-occurrence with pathogenic PALB2 variants and family history of cancer." (PMID 33195396, 2020). "Across all cancer types, there were 209 patients in the TCGA database with a total of 158 unique somatic PALB2 mutations, most of which (134/158) were missense mutations." (PMID 33193564, 2020). "To date, several ethnic-specific PALB2 recurrent mutations have been reported, and related cancer predisposition risks have been established in distinct territories." (PMID 32185139, 2020). "To evaluate our system, we selected 12 truncating PALB2 variants (red) that are known to be deleterious and associate with cancer and/or Fanconi anemia." (PMID 31757951, 2019). "In contrast to truncating variants in PALB2, the contribution of missense variants with respect to cancer risk is largely unclear." (PMID 31757951, 2019). "Identification of certain variants in genes such as PALB2 or APC have important implications for cancer surveillance in patients and their at‐risk relatives." (PMID 31592449, 2019). "Further development will need in-depth understanding of the functional properties of the variant spectrum for determining the pattern of PALB2 and defective DNA repair in genesis and cancer treatment." (PMID 30975222, 2019). "While truncating variants in PALB2 are known to increase cancer risk, the interpretation of missense variants of uncertain significance (VUS) is in its infancy." (PMID 31757951, 2019). "PALB2 is a BRCA2-interacting protein needed for the DNA repair function of BRCA2, and the spectrum of cancers in patients with the biallelic PALB2 mutation is very similar to those with biallelic BRCA2 mutation." (PMID 30840646, 2019).